ENSG00000199282
Synonyms: LOC124900344
Gene: Small nucleolar RNA gene on chromosome 13 (72,586,680 to 72,586,810, forward strand). Ensembl gene ENSG00000199282.
Gene Ontology:
Biological process: RNA processing
Cellular component: nucleolus
Homologues: Paralogues in human: SNORA9 (86% identical), SNORA9B (84% identical).